HGF (hepatocyte growth factor)
Diseases named in the same sentence as HGF in open-access papers (continued):
Sharing a sentence is not in itself a finding about the gene and the disease.
uveal melanoma (continued). "Expression of HGF in the 5 human uveal melanoma cell lines (92.1, SP6.5, MKT-BR, OCM-1, UW-1), and the functional significance of this expression has not yet been elucidated." (PMID 17261188, 2007). "Hyperactivation of cMET by HGF contributes to mUM development, and the liver, being the major source of HGF, may partially explain the metastasis of uveal melanoma cells to the liver." (PMID 36761417, 2022). "Here, we review the HGF/MET signaling biology and the role of HGF/MET blockades in uveal melanoma." (PMID 34771620, 2021). "Thus, FOXM1 contributes to the HGF-mediated protection from senescence in uveal melanoma cells treated with a CDK4/6 inhibitor." (PMID 33806615, 2021). "HGF/MET signaling plays a key role in the development of metastasis in uveal melanoma." (PMID 34771620, 2021). "Prior studies have indicated that HGF may play an important role in mediating uveal melanoma growth and metastasis." (PMID 24551032, 2014). "Moreover, silencing of SDCBP in mda-9/syntenin-high uveal melanoma cells inhibited the hepatocyte growth factor (HGF)-triggered invasion of matrigel membranes and inhibited the activation of FAK, AKT and Src." (PMID 22267972, 2012). "The present study was designed in order to analyze the expression of CXCL12, CXCL8, CXCL1, and HGF in five human uveal melanoma cell lines (92.1, SP6.5, MKT-BR, OCM-1, UW-1) and to investigate the effects of these factors on the migratory ability of the 5 cell lines." (PMID 17261188, 2007). "Demonstration of a functional role for CXCL12, CXCL8, CXCL1, and HGF in uveal melanoma may yield novel therapeutic targets." (PMID 17261188, 2007). "The STRING analysis performed in plasma samples of uveal melanoma patients for miR-454-3p showed that the MET and HGF molecules were the target proteins that mostly interact with miR-454-3p (p value: 0.000129)." (PMID 38914847, 2025). "The metastatic uveal melanoma cell lines, MEL-202 (primary) and MM28 (metastatic) were incubated with darovasertib (2, 4, 6, 8, or 10 μM) and HGF (20, 40, 60, 80, or 100 ng/mL or crizotinib)." (PMID 37576814, 2023). "Hepatocyte growth factor (HGF)/mesenchymal-epithelial transition factor (MET) signaling promotes tumorigenesis and tumor progression in various types of cancer, including uveal melanoma (UM)." (PMID 34771620, 2021). "Hepatocyte growth factor (HGF)/mesenchymal-epithelial transition factor (MET) signaling plays an important role in the metastatic formation and therapeutic resistance to uveal melanoma." (PMID 34771620, 2021). "ARF6 potentiates hepatocyte growth factor/MET signaling, which is a key player in the high rate of hepatic metastasis seen in uveal melanoma." (PMID 31320995, 2019). "The elimination of the HGF induced PI3K phosphorylation following METi treatment suggests a significant role for MET – PI3K/AKT signaling in growth and survival in uveal melanoma." (PMID 24551032, 2014). "In this context HGF and its receptor c-MET have been involved in tumor invasiveness and metastatic progression in different types of tumors, also including uveal melanoma." (PMID 22267972, 2012). "This possibility is also supported by the finding that mda-9/syntenin is involved in cell migration of uveal melanoma cells in culture and in invasiveness and activation of focal adhesion kinase (FAK), AKT and Src triggered by HGF." (PMID 22267972, 2012). "BAY11-7082 also inhibited the migration of uveal melanoma cells towards high concentrations of FBS and the uveal melanoma cell specific chemoattractant HGF." (PMID 23443086, 2012). "All 5 human uveal melanoma cell lines were shown to produce significant levels of CXCL8, CXCL1, and HGF." (PMID 17261188, 2007). "The migratory ability of the 5 human uveal melanoma cell lines was positively influenced by the four chemotactic factors tested, namely CXCL12, CXCL8, CXCL1, and HGF." (PMID 17261188, 2007).
uveal melanoma (continued). "A recent in vitro study indicated that HGF promotes resistance to MEK inhibitors by increasing the expression of the proteins, Bcl-2-like 11 (BIM)—extra-long (EL) and Bcl-2 Modifying Factor (BMF), in uveal melanoma cells." (PMID 37576814, 2023). "In human HGF knock-in NOD.Cg-Prkdc scid Il2rg tm1Wjl/SzJ mice, combination of CDK4/6 inhibitor and cMET inhibitor showed significant growth suppression in implanted metastatic uveal melanoma cells, compared to CDK4/6 inhibitor alone." (PMID 33806615, 2021). "Currently, there is no available systemic therapy for preventing or treating uveal melanoma metastases; so our focus on liver biology, and specifically on secreted growth factors like hepatocyte growth factor (HGF) is a high priority." (PMID 24551032, 2014).
cervical carcinoma (16 papers, 2014 to 2025). A carcinoma arising from either the exocervical squamous epithelium or the endocervical glandular epithelium. "HGF/c-Met is associated with the occurrence, development, and prognosis of cervical cancer." (PMID 27069297, 2016). "HGF overexpression in lesions of cervical cancer has been reported to be related to a poor prognosis." (PMID 33671013, 2021). "Hepatocyte growth factor (HGF)/c-Met pathway is related to the occurrence, development and prognosis of cervical cancer, and c-Met is significantly overexpressed in cervical squamous cell carcinoma." (PMID 28615991, 2017). "Several studies have shown that c-Met was significantly overexpressed in cervical squamous cell carcinoma and the HGF/c-Met pathway was related to the occurrence, development and prognosis of cervical cancer." (PMID 28615991, 2017). "In particular, HGF mRNA expression was detected in cervical cancer mesenchymal cells and c-Met mRNA expression in SKG-IIIa and Hela-S3 cells." (PMID 27069297, 2016). "Interestingly, these results are consistent with our previous data where HGF upregulated cyclin D1 expression in cervical carcinoma cells." (PMID 25888626, 2015). "We previously showed that stimulation of the MET receptor with HGF alone or together with stromal-derived factor-1 (SDF-1), the ligand for the CXCR4 receptor, results in migration and cytoskeletal changes in cervical carcinoma cells." (PMID 25888626, 2015). "Overexpression of HGF and the MET receptor may also stimulate proliferation in cervical carcinoma cells." (PMID 25888626, 2015).
head and neck cancer (16 papers, 2011 to 2025). A primary or metastatic malignant neoplasm affecting the head and neck. "The RTK MET, the high-affinity receptor for hepatocyte growth factor (HGF), functions as an oncogenic driver in many distinct human tumors, including gastric, lung, brain, and head and neck cancers." (PMID 38957115, 2024). "Kumar and colleagues reported an autocrine loop triggered by HGF secreted by tumor-associated fibroblasts, which acts through MET to drive glycolysis in the progression of head and neck cancer." (PMID 38957115, 2024). "Since Met has been reported to promote invasive and angiogenic effects in the tumor microenvironment, the use of HGF/Met inhibitors may afford a means of impairing tissue colonization as well as tumor vascularization in head and neck cancer patients." (PMID 21776391, 2011).
infarction (16 papers, 2008 to 2025). A localised pathological necrosis of tissue resulting from obstruction of the blood supply usually by a thrombus, an embolus, or vascular torsion. "Staining of left ventricular myocardial tissue bordering zones with infarction demonstrated a wide-spread distribution of HGF/IgG complexes; this pattern was associated with the microvasculature and arterioles as well as within myocardial tissue (n = 3 pigs)." (PMID 35295649, 2022). "Our main aim was to test the effect of sustained IGF-1 and HGF co-administration in an in vivo porcine infarction model." (PMID 27423905, 2016). "The cardiac function, myocardial perfusion scores and voltage of the HGF group improved significantly, and infarction size reduced significantly four weeks after the GTx compared to those before the GTx." (PMID 23301013, 2013). "Recently, it has been reported that HGF gene therapy improves LV remodeling and dysfunction post-infarction through promotion of cardiomyocyte hypertrophy, and that HGF plays a role in the induction of stem cell commitment to the cardiomyocyte lineage." (PMID 18795097, 2008). "Sequential release of IGF and HGF is of interest for myocardial regeneration after infarction." (PMID 36145603, 2022). "A significant percentage of implanted CPC actively proliferated and migrated from the cell sheet to the site of infarction that could probably be caused by increasing production of growth factors and cytokines in a damaged ischemic myocardium (SDF-1, HGF, VEGF, and IGF-1)." (PMID 30046593, 2018). "Furthermore, some chemokines like AGPT1 and HGF are supposed to induce immature stem cells to an injured myocardium and differentiate into large numbers of cardiomyogenic cells in vivo and in vitro after infarction." (PMID 26043119, 2015). "We aimed to determine whether mesenchymal stem cells (MSCs) carrying a hepatocyte growth factor (HGF) gene modification (HGF-MSCs) decrease the levels of arrhythmogenic substrates and reduce the susceptibility to developing VA compared with unmodified MSCs and PBS in a swine infarction model." (PMID 25360679, 2014). "The hydrogel was delivered via intramyocardial injection following infarction, and loaded either with VEGF, HGF, or both factors." (PMID 23226440, 2012). "Future studies could focus on single-cell analysis to characterize populations derived from activated epicardium, as well as the long-term effects of HGF-MSC CSs on fibrosis and cardiac remodeling during the late stages of post-infarction repair." (PMID 40806435, 2025). "Although groups treated with HGF alone and BMSC alone had comparable LVEF improvements of 16.7 ± 5.4% (p < 0.001) and 12.9 ± 4.7% (p = 0.01) at 5 weeks after infarction, the combination of BMSCs and HGF produced a marked improvement in the ejection fraction of 24.5 ± 4.2% (p < 0.001)." (PMID 27804974, 2016).
ischemic stroke (16 papers, 2011 to 2026). A stroke disorder caused by obstruction of blood flow to the brain, due to thrombotic (local blood clot formation) or embolic (due to a blood clot or other material traveling from another site) event. "Available evidence indicates that CeAD accompanied by ischemic stroke is associated with higher plasma levels of hepatocyte growth factor (HGF) and stromal cell-derived factor 1α (SDF-1α) as well as lower IL-4 concentrations, reflecting a more pronounced systemic inflammatory activation." (PMID 41570020, 2026). "HGF was also associated with central and peripheral inflammation in ischemic stroke." (PMID 34421795, 2021). "First, circulating HGF levels can be referred to predict the risk of ischemic stroke." (PMID 34421795, 2021). "In our study, the content of VEGF, basic FGF, G-CSF and HGF was significantly higher in the unstimulated saliva of patients with ischemic stroke compared to the controls." (PMID 40221607, 2025). "Here we assessed the therapeutic effects of HFSCs on ischemic stroke injury and the synthetic effect of HGF along with HFSCs." (PMID 36782269, 2023). "Hepatocyte growth factor (HGF) is a pleiotropic cytokine that shows neuroprotective function in ischemic stroke." (PMID 36782269, 2023). "Delayed recanalization after middle cerebral artery occlusion ameliorated ischemic stroke by inhibiting apoptosis via the HGF/c-Met/STAT3/Bcl-2 pathway in rats." (PMID 34421795, 2021). "In the present study, we aimed to assess whether HFSCs and HGF-modified HFSCs play a therapeutic role in ischemic stroke." (PMID 36782269, 2023). "HGF suppressed microglial activation and IL-1β expression in rats with ischemic stroke." (PMID 34421795, 2021). "Thus, studies have demonstrated that a panel of biomarkers, including complement C3, high-sensitive C-reactive protein, hepatocyte growth factor, MMP9, and anti-phosphatidylserine antibodies, can provide more comprehensive risk stratification for adverse outcomes in ischemic stroke." (PMID 39459548, 2024). "HGF is associated with coronary artery disease and ischemic stroke in patients without CKD." (PMID 35453489, 2022). "In our study, the concentration of chemotactic factors (CTACK, IL-8, MIG, MIF) and growth factors (basic FGF, G-CSF, HGF, LIF, VEGF) was significantly higher in the unstimulated saliva of patients with ischemic stroke compared to the control group." (PMID 40221607, 2025). "In this study, we demonstrated that the concentrations of basic FGF, HGF, IL-3, and LIF most effectively differentiate ischemic stroke patients from the control group (AUC = 1, sensitivity and specificity = 100%)." (PMID 40221607, 2025). "Receiver Operating Characteristic (ROC) analysis showed that salivary basic FGF, HGF, IL-3 and LIF can distinguish ischemic stroke patients from the control group with high sensitivity and specificity." (PMID 40221607, 2025).
metastatic disease (16 papers, 2009 to 2024). "Since the HGF-MET axis is frequently dysregulated in many types of cancer and MET dysregulation is associated with an increased propensity for metastatic disease and poor overall prognosis, HGF/MET inhibition has emerged as a target for anticancer therapies." (PMID 25839163, 2015). "Abnormal c-Met/HGF/SF signaling has been demonstrated in different tumors and linked to aggressive and metastatic tumor phenotypes." (PMID 19939254, 2009). "Previously, liver-borne growth factors, IGF-1 and HGF were proposed to be predictors for metastatic disease and potential therapeutic targets for UM." (PMID 36551732, 2022). "In light of the recent approval of ICIs for HNSCC as a first-line treatment in recurrent and metastatic disease, it is of interest to learn more about the connections between HGF/Met and immune checkpoints in HNSCC." (PMID 33233528, 2020). "HGF was added at 0.4 and 0.8 ng/mL, to represent HGF concentrations found in the serum of a healthy human, and a patient with metastatic disease, respectively." (PMID 30719213, 2019). "As before, these concentrations of HGF were chosen to represent those found in the serum of a patient with metastatic disease, and the concentration typically used in literature, respectively." (PMID 30719213, 2019). "In contrast, both primary and metastatic tumors developed in whole liver of mice injected with HGF (SPSS test: p < 0.005, N = 3)." (PMID 26840563, 2016). "The median HGF level was 329.1 ng/mL (1.4-1051.1) in the preoperative blood samples of 44 (71.0%) patients who underwent surgical resection as well as in the blood samples taken before chemotherapy from 18 patients (29.0%), who had metastatic disease." (PMID 36789987, 2023). "Elevated co-expression of HGF and IL-8, VEGF, and PDGF in both tumors and serum from HNSCC patients further supports the hypothesis of an interaction between HGF/c-Met signaling and these cytokines promoting angiogenesis and metastatic disease." (PMID 28441771, 2017). "Accordingly, elevated expression of RPs and Eif4a1 was also detected in both prostate primary and metastatic tumor cells, aligning with upregulated XPO1, HGF/MET, and Wnt/β-catenin downstream target expression." (PMID 38336745, 2024). "The c-MET receptor and its ligand, hepatocyte growth factor (HGF), are involved in carcinogenesis and metastatic tumor progression." (PMID 38339049, 2024). "Its ligand, hepatocyte growth factor (HGF), can be produced by stromal cells around the prostate, but also in bone, making c-Met a good target for localized and metastatic disease." (PMID 24213509, 2012). "In addition, cell lines that ectopically overexpress c-MET or HGF become transformed and metastasized in nude mice, and similarly, HGF or c-MET transgenic mice develop metastatic tumors." (PMID 28817103, 2017).
myopia (16 papers, 2008 to 2025). "Although the association of HGF variants with myopia had been previously reported and replicated in several independent studies on adults in Chinese and Caucasian populations, we were interested in studying children with high and moderate hyperopia." (PMID 30863626, 2019). "Intriguingly, HGF exhibited significant interaction with another myopia-associated gene GJD2, which also contributed to the genetic association with axial length and vitreous chamber depth." (PMID 22509107, 2012). "On APL analysis, the risk allele T for the HGF SNP, rs3735520, was found to have a statistically significant association with mild to moderate myopia versus emmetropia (p=0.002768 for SPH and 0.005609 for SE)." (PMID 19471602, 2009). "This study supports a strong association between the mild to moderate myopia group and the HGF SNP rs3735520 and the HGF haplotypes rs2286194-rs3735520-rs17501108 and rs12536657-rs2286194, and a moderate association of the extreme high myopia with rs2286194." (PMID 19471602, 2009). "The mild to moderate myopia group showed a statistically significant association with the HGF SNP, rs3735520." (PMID 19471602, 2009). "The HGF SNP, rs2286194, was found to have a statistically significant association with extreme high myopia when compared with emmetropia by APL testing (p=0.0058 for SPH and 0.0041 for SE)." (PMID 19471602, 2009). "A promising association between extreme high myopia and the HGF SNP, rs2286194, was also found (APL p=0.005763 for SPH and 0.004103 for SE)." (PMID 19471602, 2009). "But, the associations of CTGF and HGF with myopia are still unclear." (PMID 30665391, 2019). "The HGF gene has been previously reported as being associated with refractive error in multiple populations including myopia in Han Chinese as well as by ourselves for both myopia and hypermetropia in Caucasians and by others in myopia." (PMID 24416191, 2014). "Likewise, association of the hepatocyte growth factor gene (HGF) with myopia has also been reported in Chinese and Caucasians." (PMID 22509107, 2012). "Therefore, we ascertained and genotyped Caucasian family subjects biased towards high myopia and performed association analyses for polymorphisms and haplotypes of HGF and C-MET with multiple myopic refractive error phenotypes." (PMID 19471602, 2009). "Our study suggests that the HGF associations with myopia may be present in the Caucasian population, but that genotype-phenotype relationships may differ between various ethnic datasets in the complex disorder of myopia." (PMID 19471602, 2009). "For instance, the 5′ region of HGF (hepatocyte growth factor) in mouse and man may contain a polymorphism associated with early-onset extreme myopia (beyond −10 D) in the Han Chinese population." (PMID 19122830, 2008). "Molecular profiling revealed lower levels of HIF-1α and VEGF (p < 0.01), and elevated levels of PDGF-BB (p < 0.05), HGF, and IL-6 (p < 0.01) in the high myopia group." (PMID 41438149, 2025). "In other words, we reveal a significant correlation between oxidative stress with both VEGF and HGF in the same group of myopia patients." (PMID 32477165, 2020). "Genetic studies have demonstrated that myopia is related with various growth factors, such as HGF (hepatocyte growth factor), which is capable of protecting the antioxidant system by activating antioxidant genes such as catalase." (PMID 31781378, 2019). "Although there is no specific molecular marker for myopia, several molecules have been reported to be associated with myopia, which include TGF-β, FGF2, IGF signaling, HGF and MMP2." (PMID 30674274, 2019). "These SNPs are localized in both the promoter and upstream region of the HGF (hepatocyte growth factor) gene, which was previously reported as a high myopia gene in a Han Chinese population." (PMID 28032277, 2017). "HGF probably interact with GJD2 to control the axial dimension and thus influence refractive parameters, which possibly explain its association with myopia." (PMID 22509107, 2012).